CCL19 (C-C motif chemokine ligand 19)
Diseases named in the same sentence as CCL19 in open-access papers (continued):
Sharing a sentence is not in itself a finding about the gene and the disease.
latent infection (9 papers, 2012 to 2021). "In conclusion, CCL19 enhances latent infection of resting CD4+ T-cells in a subset of donors at viral TCID50 titres of 0.5–2." (PMID 27383184, 2016). "We demonstrated that while X4-tropic HIV can infect unstimulated resting CD4+ T-cells, up to half of the donors required the presence of CCL19 to establish latent infection." (PMID 27383184, 2016). "Since very low levels of CCL19 (10–100 nM) are required for priming of resting CD4+ T cells for latent infection with HIV, we used 30 and 100 nM of CCL19 for subsequent infection and immunoblotting experiments, respectively." (PMID 27459960, 2016). "We next compared the impact of virus inoculum on establishing latent infection of resting CD4+ T-cells in the presence of CCL19 versus another exogenous signal, co-culture with mDC." (PMID 27383184, 2016). "Using the CCL19 model of HIV latency, we found that in up to 50% of donors, CCL19 enhanced latent infection of resting CD4+ T-cells by CXCR4-tropic HIV in the presence of low dose IL-2." (PMID 27383184, 2016). "Conversely, untreated and CCL19-treated resting CD4+ T cells support more latent infection than productive infection." (PMID 26067822, 2015). "This study focused on the role of chemokines—especially CCL19—in HIV-1 latent infection of resting T cells: Pre-treatment of resting CD4 T cells with the chemokines CCL19, CXCL9, CXCL10, and CCL20 led to a significant increase in integrated viral DNA." (PMID 22640593, 2012). "Finally, to examine the apoptotic effects of BL-V8-310 on human primary CD4+ T-cells latently infected with HIV, the CCL19-stimulated primary cell model of latent infection was employed." (PMID 30413535, 2019). "During HIV-1 infection, the CCL19/CCR7 axis assists with establishing a latent infection." (PMID 31632965, 2019). "Here we show that CCL19 could induce the signalling cascade upstream of AP-1, indicating that chemokine signalling may also maintain latent infection after integration has occurred." (PMID 27459960, 2016). "As such, chemotactic stimulation, such as stimulating resting CD4 T cells with the chemokines CCL19/CCL21, has been shown to activate the cofilin pathway and thereby promote HIV latent infection of resting T cells." (PMID 34765923, 2021). "In contrast to CD2 signaling, prestimulation of resting CD4 T cells with anti-CXCR4 antibody, with the chemokines CCL19/CCL21, or with IP-10 (CXCL10) has been shown to promote HIV-1 latent infection of resting CD4 T cells." (PMID 34765923, 2021). "CCL19, CCL21, IL-7, and IL-15 are known to promote latent infection in resting CD4+ T-cells." (PMID 29997630, 2018). "One study that reported that CCL19 was not required to establish latent infection in vitro, typically used high titres of infectious HIV up to a multiplicity of infection (MOI) of 3, with or without spinoculation." (PMID 27383184, 2016). "In the present study, we asked whether the PI3K signalling pathway, induced by ligation of CCL19 to CCR7, played a key role in the establishment of latent infection in CCL19-treated resting CD4+ T cells." (PMID 27459960, 2016). "However, our data demonstrate that CCL19 also increases permissibility to productive infection, although its overall effect on resting CD4+ T cells increases latent infection." (PMID 26067822, 2015). "Also in agreement with previous findings, resting CD4+ T cells were made more permissive to HIV infection when exposed to the chemokine CCL19, which increases the ability of resting CD4+ T cells to support latent infection." (PMID 26067822, 2015). "Compared with CCL19, here we found that CCL28 has an advantage in inducing long-lasting serum neutralizing Abs postchallenge and more potent systemic Abs, which may be the dominant reason for the rapid removal of HSV-2 after challenge and the reduction in establishing latent infection." (PMID 33910988, 2021).
asthma (8 papers, 2011 to 2025). "The main source of CCL19 is airway smooth muscle cells and mast cells, especially in asthmatic patients with mast cells, showing high expression of CCL19, which can mediate the migration and repair of airway smooth muscle in asthma." (PMID 34630102, 2021). "Moreover, after observing increased production of CCL19 and its receptor CCR7, these investigators suggested that the CCL19 - CCR7 axis may play a role in the recruitment of fibrocytes to the lungs in patients with asthma." (PMID 21219601, 2011). "Interestingly, studies in endobronchial biopsies derived from patients with asthma reveal an increase in the expression of certain genes involved in asthma progression such as disintegrin and metalloprotease (ADAM) 33, ADAM8, eotaxin, and CCL19 in ASM layer." (PMID 36012240, 2022).
cervical cancer (8 papers, 2017 to 2025). A primary or metastatic malignant neoplasm involving the cervix. "This approach identified LAP‐TGFβ1 and CCL19 as significant mediators that bridge the genetic regulation of inflammatory pathways and cervical cancer risk." (PMID 40817807, 2025). "Also, CCL19 overexpression is associated with malignant transformation in cervical cancer." (PMID 34544443, 2021). "Knockdown of CCL19 via siRNA inhibited the proliferation of cervical cancer cells by increasing apoptosis." (PMID 29088748, 2017). "In our study, CCL19 was firstly investigated to be upregulated in tumor tissues both at the transcription and protein level in cervical cancer." (PMID 29088748, 2017). "This study highlights the emerging role of CCL19, and suggests potential target of CCL19 pathway in cervical cancer tumorigenesis." (PMID 29088748, 2017). "To further illustrate the role and function of CCL19 in cervical cancer, we knockdowned the CCL19 expression in cervical cancer cell lines ME-180 and HeLa." (PMID 29088748, 2017). "Using quantitative PCR and western blot analyses, we found that CCL19 is overexpressed in cervical cancer cell lines and tissues." (PMID 29088748, 2017). "Our results showed that silencing of CCL19 significantly inhibited cell proliferation, colony formation, migration and invasion of cervical cancer cells." (PMID 29088748, 2017). "Our results showed that inhibition of CCL19 inhibited expression of MMP-9 and MMP-2, suggesting that CCL19 increase the aggressiveness of cervical cancer cells, possibly by regulation of MMP-2 and MMP-9." (PMID 29088748, 2017). "In conclusion, these data indicate that CCL19 is abnormally expressed in cervical cancer, indicating a novel and important role for CCL19 in cervical cancer malignant transformation." (PMID 29088748, 2017). "In order to investigate the role of CCL19 in cervical cancer cell lines, three siRNA was used to knockdown CCL19 expression in ME-180 and HeLa which have the highest of CCL19 expression." (PMID 29088748, 2017). "In contrast, C‐C Motif Chemokine 19 (CCL19) and Latency‐Associated Peptide Transforming Growth Factor Beta 1 (LAP‐TGFβ1) were associated with an increased risk of cervical cancer (ORs > 1), likely due to their roles in pro‐inflammatory or immunosuppressive pathways." (PMID 40817807, 2025). "Furthermore, the elucidation of the mediating roles of LAP‐TGFβ1 and CCL19 highlights the importance of inflammatory pathways in cervical cancer pathogenesis, offering opportunities for targeted therapeutic intervention." (PMID 40817807, 2025). "Besides, we also found that all cervical cancer-derived cell line expressed higher CCL19 than the normal human cervical epithelial cell line H8, especially for ME-180 and HeLa cells." (PMID 29088748, 2017). "Therefore, inhibition of CCL19 in cervical cancer cells makes the cell phenotype be more epithelial rather than mesenchymal." (PMID 29088748, 2017). "Our findings provide new insights into the function of CCL19 in the development of cervical cancer and suggest that CCL19 might be considered as a potential target for the cervical cancer therapies in the future." (PMID 29088748, 2017). "Moreover, our IHC results showed that the positive rate of CCL19 staining was 88.71% in 62 cases of cervical cancer and 37.10% in 62 cases of peritumoral tissues." (PMID 29088748, 2017). "A large number of studies have demonstrated that chemokines are involved in the progression, migration, and survival of cancers, such as CXCL12 (ENSG00000107562), CCL21 (ENSG00000137077), and especially CCL19 (ENSG00000172724), which is associated with progression of cervical cancer." (PMID 28970820, 2017). "Besides, our study highlighted the interaction between CCL19 and cervical cancer cell proliferation, migration, invasion." (PMID 29088748, 2017). "In summary, the present study revealed that CCL19 was up-regulated in cervical cancer tissues." (PMID 29088748, 2017).
cervical cancer (continued). "Moreover, down-regulation of CCL19 expression induces apoptosis in ME-180 and HeLa cells, indicating that knockdown of CCL19 led to growth inhibition of cervical cancer in vitro might be correlated with cell apoptosis enhancement." (PMID 29088748, 2017). "Here, we confirmed that knockdown of CCL19 suppressed EMT through the downregulation of vimentin, consistent with upregulation of E-cadherin in cervical cancer cells." (PMID 29088748, 2017). "CCL19 has also been shown to be overexpressed in cervical cancer tissue and cell lines with siRNA-induced a reduction in CCL19 inhibiting cervical cancer cell proliferation and increased levels of apoptosis, suggesting that CCL19 via CCR7 activation is a driving force of cervical cancer progression." (PMID 35203305, 2022). "Using IHC, the CCL19 expression levels were detected in a total of 62 cervical cancer and adjacent non-cancerous tissues." (PMID 29088748, 2017). "CCL19 was higher expressed in cervical cancer cell lines (C33A, HeLa, CaSki, SiHa, and ME-180) than in normal human cervical epithelial cell line H8." (PMID 29088748, 2017). "However, the role of CCL19 in cervical cancer has not been comprehensively studied until recently." (PMID 29088748, 2017). "However, whether or not CCL19 is involved in progression of human cervical cancer needs further investigation." (PMID 29088748, 2017). "However, whether or not CCL19 is involved in EMT of human cervical cancer needs further investigation." (PMID 29088748, 2017).
Sjögren’s syndrome (8 papers, 2018 to 2026). "Cxcl9, Ccl19 and Epsti1 have been implicated in Sjögren syndrome in humans or animal models." (PMID 30347820, 2018). "In Sjögren’s syndrome, the expression of CCL19/CCR7 is significantly elevated in salivary gland tissue." (PMID 41481752, 2026). "Moreover, those are present in Sicca syndrome; however, in this condition, the cluster presents low expression of CCL19, most likely reflecting the decreased level of inflammation and lower transcripts of TNFα and IFNγ in Sicca." (PMID 39747819, 2025). "Interestingly, in addition to its pathogenic role, this pathway can be exploited as a biomarker of disease as we showed that LTα expression correlates with CCL19 levels and distinguishes patients with autoimmunity and dryness (Sjögren’s syndrome) from patients with dryness only (sicca patients)." (PMID 35508704, 2022).
colon cancer (7 papers, 2021 to 2025). "Previously, it was shown that INHBA and CCL19 exhibit opposite modes of expression in colon cancer, with INHBA being upregulated while CCL19 is concurrently downregulated." (PMID 38329386, 2024). "In other solid tumors, such as ovarian and colon cancers, CCL19-expressing embryonic endothelial progenitor cells and mesenchymal stem cells functioned to activate the local TIME and led to a good therapeutic effect." (PMID 35550569, 2022). "This response may, at least in part, be due to the CCL19-mediated recruitment of immune cells, which may induce the host immune response against the colon cancer." (PMID 35203305, 2022). "In addition, CCL19 functioned as an immune-modulator for colon cancer therapy by closely communicating with DCs, T cells and B cells, thus regulating the adaptive immune responses." (PMID 35550569, 2022). "This latter study proved the ability of an HERV-H-derived peptide to increase the production of CCL19, and its role as a chemo attractive factor in recruiting an elevated number of immunosuppressive immune cells in HERV-H+ CCL19+ colon cancer tissues." (PMID 35056043, 2022). "In contrast to the ERK1/2 phosphorylation response to CCR7/CCL19 activation observed in immune cells, the colon cancer cells did not appear to express functional CCR7, since the cells failed to activate signaling pathways via CCL19 or CCL21 to ERK1/2." (PMID 35203305, 2022).
HIV-1 infection (7 papers, 2017 to 2025). The type species of lentivirus and the etiologic agent of acquired immunodeficiency syndrome (AIDS). "We used CD3+CD4+CD45RO+CCR7+ central memory T cells (CMT) for HIV-1 infection and culture in the presence of CCL19 to establish HIV latent infection." (PMID 32792548, 2020). "In this study, two different latency models based on CCL19 or IL-7 treatment before HIV-1 infection were used." (PMID 28539614, 2017). "We have previously demonstrated that latent HIV-1 infection could be established in CMTs after in vitro culture with CCL-19 and reactivated by stimulation with phytohaemagglutinin (PHA) or IDB." (PMID 36742330, 2023). "CCL-19 neither elicits T cell activation nor induces CCR5 or CXCR4 expression, but enhances cis HIV-1 infection of resting CD4+ T cells." (PMID 33688006, 2021).
influenza infection (7 papers, 2010 to 2025). "The essential requirement for CXCL13 or CCL19/21 in influenza‐induced pulmonary TLSs has been dissected in splenectomized mice lacking CXCL13 and/or CCL19/21 (paucity of lymph node T cells, plt/plt)." (PMID 40884054, 2025). "The loss of Ccl19 leads to impaired iBALT formation and B- and T-cell responses to influenza infection in mice, suggesting that Ccl19 expression in the lungs plays a crucial role in organizing lymphoid tissues." (PMID 39768150, 2024). "Notably, transcriptional studies in lung tissues of Estriol treated mice post influenza A infection revealed a correlation between upregulation of CCL19 and CCL22 genes with reduced lung inflammation and pathology due to influenza." (PMID 36119026, 2022).
Stroke (7 papers, 2015 to 2025). Sudden impairment of blood flow to a part of the brain due to occlusion or rupture of an artery to the brain. "Subsequent brain infiltration of Tsa cells is orchestrated by CCL19 derived from a specific endothelial cell subset after stroke via the CCL19/CCR7 axis." (PMID 40659887, 2025). "CCL19 was elevated in the samples from patients with AIS compared with those from non-stroke controls, as determined by qPCR and western blot analysis." (PMID 40659887, 2025). "Our analysis revealed that in addition to being expressed in a specific subset of endothelial cells post-stroke, CCL19 exhibited low baseline expression predominantly in stromal cells under normal conditions." (PMID 40659887, 2025). "Flow cytometry combined with qPCR analysis confirmed the increased expression of Ccl19 in endothelial cells after stroke compared with that in the sham group." (PMID 40659887, 2025). "Compared with that in the sham group, Ccl19 was highly expressed only in the Endo-7 subset from the stroke group." (PMID 40659887, 2025). "CCL19 has previously been found to be upregulated following stroke after damage to the intestinal epithelium and has been shown to facilitate T-cell migration to the insult site and microglial activation following stroke." (PMID 36825211, 2022). "TNFβ (also known as lymphotoxin alpha) and TNFRSF9 (also known as CD137), which activate downstream inflammatory pathways, increasing inflammation and CCL19, a protein involved in arteriole growth following ischemia that is correlated with worse outcome following stroke." (PMID 40703679, 2025). "Notably, we found that the proportion of Endo-7, which highly expresses the chemokine Ccl19, was significantly increased in the peri-infarct areas of stroke mice." (PMID 40659887, 2025). "Additionally, sequence variations in the promoter regions of CCL19 and CCL21 have been associated with an increased susceptibility to myocardial infarction, while genetic predisposition to elevated circulating levels of CCL2 correlates with a heightened risk of stroke." (PMID 40236901, 2025). "CCL19 and CCL20 are sensitive to hypoxia, inflammation, and edema in the brain and can be up-regulated in the early stage of cerebrovascular disease; they are important indicators of stroke." (PMID 40003312, 2025). "However, the expression of CCL2, CCL3, CCL4, CCL7, and CXCL2 was strongly increased after stroke, whereas CCL19, CCL20, and CXCL5 expression levels were not changed." (PMID 26640428, 2015).
lupus (6 papers, 2013 to 2025). "In our lupus model, increasing proinflammatory cytokines such as Cxcl13, Ccl19, Ltβ, and Baff mRNA levels trigger the TLOs formation." (PMID 40651955, 2025). "The aim of this study was to investigate the correlation between IFN-α-induced chemokines CCL2, CXCL10 and CCL19 and disease activity in patients with systemic lupus erythematosus." (PMID 35207538, 2022). "Two different combined inflammatory and lymphoid chemokine scores were investigated using CCL2, CXCL10 and CCL19 (score used successfully in lupus) and CXCL9, CXCL10, CXCL13 and CCL19 data." (PMID 24278364, 2013). "For example, the serum levels of the IFN-α-induced chemokines CCL2, CXCL10 and CCL19 were found to correlate with lupus patient age and disease duration and thus have implications for monitoring disease activity and the determining the degree of organ damage in SLE." (PMID 37198402, 2023). "Levels of chemokines CCL2, CXCL10 and CCL19 in lupus patients’ serum were measured by ELISA." (PMID 35207538, 2022). "We found that expression of CCL2, CCL3, CCL4, CCL5, CCL8, CCL19, and CXCL10 increased 1.6–5.6-fold in the kidney of lupus-prone MRL.Faslpr mice with advancing age from 9 to 16 weeks." (PMID 37567910, 2023). "We also found that expression of CCL2, CCL3, CCL4, CCL5, CCL8, CCL19, and CXCL10 increased 1.6–5.6-fold in the kidney of lupus-prone MRL.Faslpr mice with advancing age from 9 to 16 weeks." (PMID 37567910, 2023). "For example, secretion levels of CCL2, CCL3, CCL4, CCL5, CCL19, CXCL10, and CXCL12 are increased in the kidney of lupus-prone mice and SLE patients during the development of nephritis." (PMID 37567910, 2023). "At the human disease level, serum levels of interferon-controlled chemokines (e.g. CCL19 and CXCL10) have been found to correlate with current lupus activity, disease flare-up, and disease remission." (PMID 26981635, 2016). "Though CCL19 and CXCL10 levels differentiated patients with active SLE (with SLEDAI ≥6) from inactive SLE (with SLEDAI ≤2), similar comparison results did not occur between patients with intermediate (with SLEDAI between > 2 and <6) and low lupus activity." (PMID 26981635, 2016).
multiple sclerosis (6 papers, 2015 to 2026). A progressive autoimmune disorder affecting the central nervous system resulting in demyelination. "Research on multiple sclerosis indicates that cerebrospinal fluid levels of CCL19 correlate with the numbers of T cells and CCR7 + dendritic cells." (PMID 41481752, 2026). "Nonetheless, CCL19 in particular has been studied in neuroinflammation-related diseases such as multiple sclerosis, although here the levels were increased rather than decreased as found in our study." (PMID 34602080, 2021). "In contrast, Ccl19 is upregulated in the brain of patients with multiple sclerosis and seems to contribute to the pathological maintenance of immune cells in damaged brain regions, although its levels are not simply associated with inflammation in these patients." (PMID 32365077, 2020).